ZMAT4 (zinc finger matrin-type 4)
Synonyms: FLJ13842
Tractability: PROTAC: ubiquitination databases record sites on it; its protein half-life has been measured.
Gene: Protein-coding gene on chromosome 8 (40,530,590 to 40,897,833, reverse strand). Ensembl gene ENSG00000165061.
Subcellular location: Nucleus
Subcellular location (Human Protein Atlas): Nucleoli; Nucleoplasm
Gene Ontology:
Molecular function: protein binding; nucleic acid binding; zinc ion binding
Cellular component: nucleus
Genetic constraint (gnomAD): Loss-of-function variants: 15 observed, 24.71 expected, observed/expected ratio (o/e) 0.61, 90% interval 0.41 to 0.94. The upper end of that interval is the gene's LOEUF score, 0.94, which puts it in group 3 of 6, group 1 being the genes least tolerant of losing a copy. Missense variants: 215 observed, 246.94 expected, observed/expected ratio (o/e) 0.87, 90% interval 0.78 to 0.98. Synonymous variants: 105 observed, 97.73 expected, observed/expected ratio (o/e) 1.07, 90% interval 0.92 to 1.26.
Homologues: Orthologues: chimpanzee ZMAT4 (99% identical), dog ZMAT4 (98% identical), pig ZMAT4 (98% identical), rabbit ZMAT4 (97% identical), guinea pig ZMAT4 (96% identical), mouse Zmat4 (95% identical), rat Zmat4 (94% identical), macaque ZMAT4 (88% identical), zebrafish zmat4a (75% identical), zebrafish zmat4b (65% identical), Drosophila melanogaster dbf (23% identical), Drosophila melanogaster CG1231 (23% identical). Paralogues in human: ZNF346 (39% identical), ZMAT1 (29% identical), ZNF385B (24% identical), ZNF385C (24% identical), ZMAT3 (21% identical), ZNF385D (19% identical), ZNF385A (18% identical), ZMAT2 (11% identical), KRCC1 (1% identical).
Diseases named in the same sentence as ZMAT4 in open-access papers:
ZMAT4 is named in the same sentence as 11 diseases in open-access papers, as found by Europe PMC text mining. Sharing a sentence is not in itself a finding about the gene and the disease. The quoted sentences say what the papers report.
myopia (6 papers, 2016 to 2024). "Though few studies have been conducted on the function of ZMAT4, it has been implicated in myopia as well as thyroid cancer." (PMID 36982708, 2023). "Of note, rs7829127 and rs2137277, located in intron 1 of ZMAT4, were found to be associated by both GWAS and meta-analysis with the risk of high myopia in the Han-Chinese." (PMID 36982708, 2023). "Hence, the current approach of testing for non-additive effects provides further evidence, albeit circumstantial, linking the 3 variants to specific genes likely to have causal roles in myopia: ZMAT4, RD3L and LAMA2." (PMID 32227305, 2020). "Common genetic variants at those ZMAT4 and BMP4-CDKN3 loci have been previously reported to be associated with MSE, and high myopia, especially in Asian populations." (PMID 37351342, 2023). "The current work brings the number of independently replicated gene-by-education interactions for myopia to 3 (ZMAT4, GJD2 and RBFOX1)." (PMID 36395078, 2022). "Researchers indicate that PAX6 rs644242, ZC3H11B rs4373767 and BICC1 rs7084402, VIPR2 rs885863 and rs6979985, ZMAT4 rs7829127, TNKS rs4840437 and rs6989782, PDGFRA rs2114039, SOX2 rs4575941, FGF10 rs339501, rs2973644, and rs 79002828 are associated with severe myopia (moderate and extreme myopia)." (PMID 38660258, 2024).
schizophrenia (2 papers, 2023 to 2024). A major psychotic disorder characterized by abnormalities in the perception or expression of reality. "The remaining genes (G3bp2, Cpne7, Atcay, Zmat4, and Nxph1) of the unique LS genes are generally understudied in their role in regulating behavior, although Zmat4 is associated with schizophrenia." (PMID 38263132, 2024). "Some of these genes (RARB, ZMAT4) were correlated with grey matter volume differences between patients with schizophrenia and healthy control." (PMID 36833173, 2023).
glaucoma (1 paper, 2023). Increased pressure in the eyeball due to obstruction of the outflow of aqueous humor. "rs6474264, identified in intron 5 of ZMAT4 as being nominally significant by both measures, is protective of glaucoma medication non-adherence." (PMID 36982708, 2023).
liver cancer (1 paper, 2022). An epithelial or non-epithelial malignant neoplasm that arises from the liver. "We detected multiple genomic HBV integrations in two distinct types of liver cancer, with recurrent events at TERT, ZMAT4, MET, ANKFN1, PLXNB2 in ICC, and TERT, ALKBH5 in CHC." (PMID 36123506, 2022).
ZMAT4 also shares sentences with these, for which no sentence is quoted: tumor (2 papers); cancer (1); colon adenocarcinoma (1); hepatocellular carcinoma (1); prostate carcinoma (1); Spinocerebellar Ataxia (1); thyroid cancer (1).